RNU6-146P (RNA, U6 small nuclear 146, pseudogene)
Gene: Small nuclear RNA gene on chromosome X (3,607,258 to 3,607,365, reverse strand). Ensembl gene ENSG00000207332.
Homologues: Orthologues: chimpanzee U6 (98% identical), macaque U6 (94% identical), macaque U6 (91% identical), dog U6 (82% identical), pig U6 (82% identical), rat U6 (80% identical), guinea pig U6 (77% identical). Paralogues in human: RNU6-941P (98% identical), RNU6-322P (89% identical), RNU6-15P (86% identical), RNU6-1316P (85% identical), RNU6-166P (85% identical), RNU6-25P (85% identical), RNU6-26P (85% identical), RNU6-35P (85% identical), RNU6-41P (85% identical), RNU6-1 (84% identical), RNU6-1060P (84% identical), RNU6-1145P (84% identical), and 1285 more.